CXCL9 (C-X-C motif chemokine ligand 9)
Diseases named in the same sentence as CXCL9 in open-access papers (continued):
Sharing a sentence is not in itself a finding about the gene and the disease.
retinitis (1 paper, 2022). Inflammation of the retina. "To validate whether the CXCR3-CXCL 9, 10, 11 axis is over-expressed similarly in case of retinitis (HR) and gastro-enteric (HG) patients belonging to group 1, we compared the relative mRNA expression of some of the components of the CXCL9, 10, 11-CXCR3 axis along with some downstream effectors." (PMID 35538132, 2022). "When mRNA expression pattern was compared between the two groups it showed that the expression of CXCL9 and CXCL10 was significantly higher in case of retinitis patients whereas that of CXCL11 was higher in case of the patients with gastro-enteric disease." (PMID 35538132, 2022). "We found that in HIV patients with HCMV induced end-organ diseases the components of the CXCL9, 10, 11-CXCR3 chemokine pathway is highly expressed with significant differences existing among patients with retinitis and gastrointestinal disease." (PMID 35538132, 2022).
sarcoma (1 paper, 2025). A usually aggressive malignant neoplasm of the soft tissue or bone. "Previous studies have reported that CXCL9:SPP1 macrophage polarity is a good choice for selecting anti‐ or pro‐tumor macrophages in sarcoma, we also examined changes in the CXCL9:SPP1 polarity of PBS‐BMDMs and OCDM‐BMDMs after 24 h of coculture with apoptotic OS cells." (PMID 40056029, 2025).
scoliosis (1 paper, 2012). A congenital or acquired spinal deformity characterized by lateral curvature of the spine. "Mental QoL (i.e. MSC) was related to the genes CXCL9 (β = −3.6, p = 0.001) and CXLC11 (β = −3.4, p = 0.002), after controlling for age and the presence of severe scoliosis, which were both no longer significantly related to QoL." (PMID 23049769, 2012).
scrub typhus (1 paper, 2014). Scrub typhus is a rare dust mite-borne infectious disease caused by the Orientia tsutsugamushi bacterium and characterized clinically by an eruptive fever which is potentially serious. "Thus, modulating the level and timing of IFN-γ and CXCL9/10/11 production may be a potential therapeutic option in scrub typhus." (PMID 25254971, 2014).
secretory otitis media (1 paper, 2024). "It has recently been shown, in secretory otitis media (SOM), that different inflammatory mediators, such as CXCL1, IL-16, IL-8, IL-17, IL-1β, CXCL10, and CXCL9, were found in high concentrations in middle ear fluids, in association with the presence of bacterial and viral nucleic acid levels." (PMID 38541021, 2024).
staphylococcus aureus pneumonia (1 paper, 2023). An pneumonia caused by infection with Staphylococcus aureus. "Likewise, the chemokines CXCL9 and CXCL10 had the best sensitivity, specificity, and predictive power to differentiate between S. pneumoniae and Staphylococcus aureus pneumonia." (PMID 37893128, 2023).
stomach adenocarcinoma (1 paper, 2020). "High expression of CXCL9 and CXCL10 correlated positively with infiltrating levels of CD4+ T and CD8+ T cells in stomach adenocarcinoma." (PMID 33323542, 2020). "Expression of CXCL9 and CXCL10 was positively correlated with infiltrating levels of CD8+ T cells in stomach adenocarcinoma." (PMID 33323542, 2020).
streptococcal pharyngitis (1 paper, 2009). Inflammation of the throat due to Streptococcus pyogenes. "The three CXC chemokines CXCL9, 10, and 11 are closely related, act through the same receptor (CXCR3), are expressed in the context of streptococcal pharyngitis, are antibacterial towards S. pyogenes, and are induced by the cell wall-anchored M protein from S. pyogenes." (PMID 19274094, 2009).
synovitis (1 paper, 2025). Inflammation of a synovial membrane. "With respect to clinically relevant outcome measures, Cxcl9-deficient mice were even protected from cartilage degeneration and synovitis." (PMID 40047894, 2025).
tick-borne encephalitis (1 paper, 2019). Tick-borne encephalitis is caused by an arbovirus of the Flaviviridae family (tick-borne encephalitis virus, TBEV), transmitted principally by the bite of the Ixodes ricinus tick. "For example the Quotient value of chemokine CXCL9 was a better indicator of symptoms resolution in tick-borne encephalitis patients than CSF or serum CXCL9 concentration." (PMID 30953468, 2019).
tongue squamous cell carcinoma (1 paper, 2023). A squamous cell carcinoma that arises from the tongue. "However, CXCL9/CXCR3 axis has been reported to activate Akt signaling pathway, accompany EMT and cytoskeleton rearrangement, and promote invasion and metastasis in tongue squamous cell carcinoma." (PMID 36750966, 2023).
trisomy 21 (1 paper, 2024). A chromosomal disorder consisting of the presence of an extra chromosome 21. "Ontologies such as response and defense against viruses, antimicrobial humoral immune responses mediated by antimicrobial peptides, and the regulation of myoblast fusion were associated with 20 genes in the Trisomy 21 with CHDs datasets (GSE196443 and GSE217557), including GNLY, IFI44L, and CXCL9." (PMID 39596121, 2024).
urticaria (1 paper, 2018). A vascular reaction of the skin characterized by erythema and wheal formation due to localized increase of vascular permeability. "At day 90, only 3 of the patients with the extreme cytokine value had an AR; the patients with the highest levels of IL-10 and IL-17A experienced grade 1 toxicities (urticaria and AR, respectively), while the patient with the highest levels of CXCL9 experienced grade 3 urticaria." (PMID 29967609, 2018).
vaginal infection (1 paper, 2011). "Virus is able to reach the central nervous system more quickly after vaginal infection in mice deficient in CXCL10, and trafficking of NK cells and HSV-specific CD8+ T-cells (but not CD4+ T-cells) to infected tissue is impaired in both CXCL9 and CXCL10-deficient mice." (PMID 21283640, 2011).
vasculitis (1 paper, 2015). "When inflammation occurs, MIG/CXCL9 and TARC/CCL17 can stimulate Th1 and Th2 cells secreting cytokines to regulate the immunoreaction during the development of vasculitis in KD, and so plasma MIG/CXCL9 levels increase with the development of a serious inflammation." (PMID 26337791, 2015). "So the plasma levels of MIG/CXCL9 and TARC/CCL17 can reflect the numbers of activated Th1 and Th2 cells in vasculitis sites in KD patients." (PMID 26337791, 2015). "Since Th1 and Th2 cells can be induced by MIG/CXCL9 and TARC/CCL17 and migrate to vasculitis sites in KD, the levels of activated Th1 and Th2 cells should have an appropriate ratio and play a well-balanced role." (PMID 26337791, 2015). "However, when vasculitis develops into CAL, plasma MIG/CXCL9 levels could be negatively feedback regulated while TARC/CCL17 increase persistently." (PMID 26337791, 2015).
viral hepatitis (1 paper, 2023). An acute or chronic inflammation of the liver parenchyma caused by viruses. "For each etiology-based subgroup (NAFLD, ALD, viral hepatitis, and “other”), CXCL5, CXCL9, and CXCL10 were significantly elevated in HCC patients and might be used as etiology-independent HCC-discriminant chemokine panel." (PMID 36982370, 2023).
viral meningitis (1 paper, 2019). Inflammation of the membranes surrounding the brain and spinal cord due to a viral infection. "Also, in viral meningitis, multiple cytokines (16/36) were elevated and we could confirm previously reported results for CXCL9, CXCL11, and IFNγ." (PMID 31727097, 2019). "The chemokines CCL3, CCL7, CCL8, and CXCL9 were all significantly elevated in patients with LNB and bacterial and viral meningitis." (PMID 31727097, 2019).
vivax malaria (1 paper, 2019). "Patients with HBV monoinfection presented the same number of variables which concentrations were increased (mainly IFN-γ, TNF-α, IL-6 and CXCL9), when compared to asymptomatic vivax malaria monoinfection, but only significant decrease of one variable (also IL-4)." (PMID 31233500, 2019).
Yersinia infection (1 paper, 2008). "Furthermore, approach II revealed genes (interferon induced genes such as interferon inducible GTPase 1 (IIGP1), CXCL9, as well as VEGF-α) which were highly induced after Yersinia infection but which were lower expressed after lethal ΔyopH infection compared to sublethal or lethal pYV+ infection." (PMID 18803824, 2008).
tumor (1,509 papers, 2003 to 2026). "CD206+ TAMs can produce CXCL9, are associated with antigen presentation and regulate anti-tumor cDC1-CXCR3+ lymphocyte assembly in the TME." (PMID 41048107, 2025). "SAA2 expression was linked to the presence of burrs on tumour edges, and CXCL9 expression was associated with age of onset and tumour stage." (PMID 41228202, 2025). "That study identified a population of MHCIIhigh CCR7neg cDC1s associated with CXCL9 expression at the stroma‐tumour interface, in apparent contrast with our findings of Cxcl9 cDC1s enrichment in the tumour parenchyma." (PMID 40745918, 2025). "Nevertheless, the mechanisms underlying the programming of CXCL9+ macrophages remain poorly understood, thereby hindering the development of tumor treatment strategies based on this antitumor population." (PMID 41321309, 2025). "By inducing immunogenic tumor cell lysis and releasing damage-associated molecular patterns (DAMPs), type I interferons, and chemokines (CXCL9/10), they enhance the recruitment of CD8+ T cells into the tumor milieu." (PMID 41262250, 2025). "ISGs expressed by some tumour‐associated cDC1s include CXCL9 and CXCL10, which are important for the recruitment and localisation of CD8+ T cells." (PMID 40745918, 2025). "CXCL9, a chemokine involved in modulating immune responses by promoting tumor-infiltrating lymphocytes (TILs), has been associated with a favorable prognosis in ER-negative/HER2-negative breast cancer, correlating with improved survival and higher TIL levels." (PMID 40205245, 2025). "Recruit effector T-cell into the tumor.Increased expression of CXCL9/10 linked to favorable prognosis." (PMID 40943634, 2025). "Old tumor cells showed reduced expression of interferon-related genes, particularly the T cell-recruiting chemokines Cxcl9 and Cxcl10, linked to their altered chromatin accessibility." (PMID 41332581, 2025). "Poor tumor infiltration by T cells has been attributed to potent epigenetic silencing of the genes encoding the Th1-type chemokines CXCL-9 and CXCL-10 in tumors." (PMID 39996769, 2025). "We reveal two distinct cDC1 activation states characterised by differential expression of genes linked to anti‐tumour immunity, including Cxcl9 and Il12b." (PMID 40745918, 2025). "CXCL9 expression is also associated with a higher frequency of cytotoxic T-cells in the tumor microenvironment of DLBCL." (PMID 41008822, 2025). "In a murine PDAC model, we found that intrinsic loss of SIN3B within tumor cells enhances CD8+ T cell infiltration by increasing the secretion of IFNγ‐induced chemokines CXCL9 and CXCL10." (PMID 39316363, 2024). "CXCL9 of tumor-associated macrophages inhibited CD8+ T-cell infiltration and impaired anti-PD1 treatment." (PMID 38887558, 2024). "Anti-Tim-3 antibodies caused tumor DCs to produce more CXCL9, which increased activation and lymphocyte infiltration in animal models of breast cancer." (PMID 38418707, 2024). "The expression of CXCL9 by tumor-associated macrophages regulates the recruitment and positioning of CXCR3+ CD8 T cells, underlying the clinical response to anti-PD(L)-1 treatment." (PMID 39076974, 2024). "Sin3B‐deficient tumor cells exhibited amplified CXCL9/10 secretion in response to Interferon‐gamma (IFNγ), creating a positive feedback loop via the CXCL9/10‐CXCR3 axis, thereby intensifying the anti‐tumor immune response against PDAC." (PMID 39316363, 2024). "With regard to the source of CXCL9, we identified monocytes and macrophages as main producers, which is in line with a report demonstrating that depletion of CXCL9-expressing tumor-associated macrophages hamper anti-tumor responses." (PMID 39885986, 2024). "We further suggest that CD57+ T-cell infiltration is associated with CXCL9 expression in tumor cells, and specifically in high-risk patients, which needs to be investigated functionally in future studies." (PMID 39001353, 2024).
tumor (continued). "For example, increased expression of CXCL9 by tumor-associated DCs has been shown to enhance their interaction with CXCR3-expressing CD8+ T cells in a murine model of breast cancer." (PMID 39596815, 2024). "Blocking EZH2 in orthotopic, murine, KPC tumors, treated with MEK and CDK4/6 inhibitors, subsequently led to an increase in intra-tumoral CCL2 and CXCL9/10 production and was associated with NK- and T-cell influx and anti-tumor responses." (PMID 38339310, 2024). "In vivo, tumor growth was rescued by specific knockdown of Cxcl9&10 in Sin3B‐deficient PDAC cells, accompanied by a significant decrease in tumoral infiltrating CD8+ T cells." (PMID 39316363, 2024). "Macrophages marked by high CXCL9 expression (Mph_01_CXCL9) are often associated with a more favorable prognosis in tumor patients." (PMID 39239526, 2024). "A recent report on over 1000 patients with various tumor types indicated that CXCL9 gene expression and tumor mutational burden are highly effective markers for predicting the response to ICI." (PMID 38590525, 2024). "CXCL9 is also associated with T cell infiltration of cutaneous tumors, resulting in tumor suppression." (PMID 38786066, 2024). "While an imbalanced respiratory tract microbiome has been associated with tumor progression, a more diverse lung microbiome is correlated with higher levels of CXCL9, a chemokine associated with better immune response in the tumor." (PMID 38903504, 2024). "We also found that abnormal expression of CXCL9 (P = 0.0201), CXCL11 (P = 0.0385), and CXCL13 (P = 0.0288) was closely associated to tumor stage, and the expression of CXCL9, CXCL11, and CXCL13 decreased with the increase of stage." (PMID 36798787, 2023). "An enhanced expression of CXCL9 in cancer tissue than healthy tissue was also observed in the second Chinese study, where CXCL9 expression levels were associated with tumor stage and survival." (PMID 37228491, 2023). "LIF can regulate CXCL9 in tumor-associated macrophages and prevent tumor infiltration of CD8+ T cells, explaining the slower CD8+ TILs kinetics seen with oBHV + ICI." (PMID 36831636, 2023). "On the other hand, another study has found that CXCL9 is associated with poor patient outcomes and described it as a tumor promoter due to T cell suppression." (PMID 36980700, 2023). "Herein, we demonstrate that AAV encoding for the lymphotactic chemokine CXCL9 can be leveraged to engage the immune system to recognize and attack tumor cells by modulating anti-PD-1 immunotherapy in the combinatorial setting." (PMID 38014191, 2023). "Together these data demonstrate that AAV6 intratumor delivery of CXCL9 results in focal and durable expression of encoded transgene, where tumor-reactive astrocytes are the target of AAV6 transduction." (PMID 38014191, 2023). "CXCL9 is one of the immune activation chemokines; its expression plays a crucial role in anti-tumor immunity and is associated with improvements in different types of cancer patients’ survival and overall good clinical outcomes." (PMID 38067251, 2023). "In this study, single-cell and pan-cancer analysis revealed that CXCL9/10 plays a role in M1-polarized tumor-associated macrophages in ccRcc patients." (PMID 37540227, 2023). "In HCC, CXCL9 is associated with the recruitment of tumor-infiltrating immune cells (mainly CD4+ and CD8+ lymphocytes) shaping the TME and possibly amplifying anti-tumor responses of cytotoxic T cells." (PMID 36982370, 2023). "Conversely, fractions of regulatory T (Treg) cells, T follicular helper (Tfh) cells, B cells and CXCL9+ tumor-associated macrophages (TAMs) were largely increased in tumors (all P < 0.0001)." (PMID 36928818, 2023). "The inhibitory effects of IL-12 on tumour vasculature were also associated with increased levels of the IFN-γ-inducible chemokine ligands CXCL9 and CXCL10 (IP-10) and decreased production of vascular endothelial growth factor (VEGF)." (PMID 37629081, 2023).
tumor (continued). "The CXC chemokine subfamily member CXCL9 encodes secreted proteins that play essential roles in disease processes, such as inflammation, immune regulation, tumor metastasis, and angiogenesis." (PMID 37644593, 2023). "It was reported that myeloid cells, including tumor-associated macrophages and DCs, in peripheral blood mononuclear cells (PBMCs) secrete CXCL9 in patients with epithelial ovarian cancer." (PMID 37046033, 2023). "CD40 agonist also increased Cxcl9/Cxcl10 in KPC2a tumors and Cxcl9/Cxcl10 colocalized with both tumor-associated macrophages (TAMs) and tumor cells." (PMID 36472588, 2023). "The third most frequently implicated hallmark (14 proteins) was “tumor-promoting inflammation”, including markers such as CXCL9, CXCL13, CXL17, IL6, and IL2-RA." (PMID 37264016, 2023). "We previously reported that anti-VEGF lenvatinib effectively recruits GZMK+ CD8 T cells to the tumor site through CXCL9 released from tumor-associated macrophages; however, it also enriched intratumoral stroma by upregulating fibrosis-related pathways." (PMID 37894439, 2023). "In summation, intra-tumor delivery of AAV6 encoded CXCL9 results in the production of a pro-lymphocyte chemotactic gradient by transduced tumor-reactive astrocytes." (PMID 38014191, 2023). "CXCL9-expressing tumor-associated macrophages can recruit a large number of CXCR3-expressing stem-like CD8+ T cells into TME, thus improving the efficacy of anti-PD(L)-1 treatment." (PMID 36090326, 2022). "High expression of CXCR3 and CXCL9/10 has been associated with a poor prognosis, tumor growth, and increased risk of metastasis." (PMID 36180422, 2022). "Cytotoxic CD8+ T cells secrete IFN-γ, which suppresses tumor angiogenesis by inhibiting the proliferation of ECs and upregulating cytokine-encoding genes (e.g., CXCL9, CXCL10, and CXCL11)." (PMID 35759090, 2022). "While CXCL9 is classically associated with M1 macrophage, the chemokine also binds to tumor cells expressing CXCR3 receptor and exhibit pro-tumor effects." (PMID 36132332, 2022). "Bortezomide is able to induce ICD in these models and especially type I IFN and CXCL9 production in a STING-dependent manner which is associated with an increase in the lymphocytes at the tumor site." (PMID 36429101, 2022). "Tumor-associated dendritic cells can produce high levels of CXCL9, which promotes tumor progression by increasing programmed death-ligand 1 (PD-L1) expression through the activation of CXCR3-related signals." (PMID 36504808, 2022). "These two signaling interactions have totally different impacts on tumor growth: CXCL9 with paracrine signaling mainly has tumor-suppression effects, and CXCL9 with autocrine signaling causes cancer cell proliferation and metastasis." (PMID 36362062, 2022). "CXCR3 (C-X-C motif chemokine receptor 3) participates in tumorigenesis and promotes the formation of tumor-associated blood vessels by binding to its cognate CXC chemokine ligand 9(CXCL9)/10/11." (PMID 36479091, 2022). "This association between tumor Secretory cDC2 and T cell inflammation suggests that T-cell-attracting chemokines, such as CXCL9, are not only overexpressed by Secretory cDC2 at the transcriptomic level but also at the protein level in cancer." (PMID 35418195, 2022). "A large-scale meta-analysis showed that clonal tumor mutation burden and CXCL9 expression were the strongest predictors of ICI responses across seven tumor types." (PMID 35954313, 2022). "Tumor-associated myeloid cells expressing CXCL9/10 have previously been described and attributed important immunotherapy-induced antitumor functions." (PMID 34650042, 2021). "CCL5 from tumor cells or tumor-associated myeloid cells appears to license CXCL9 production almost exclusively from inflammatory CD68+ macrophages and CD11c+ DCs within the TME." (PMID 34354714, 2021).